UBD (ubiquitin like modifier D)
Diseases named in the same sentence as UBD in open-access papers (continued):
Sharing a sentence is not in itself a finding about the gene and the disease.
tumor (continued). "For instance, UBD’s pro-apoptotic effects in SKCM may counteract tumor growth, whereas its genomic destabilizing properties in UVM could exacerbate malignancy." (PMID 41347086, 2025). "However, our study is unique in that it is the first to uncover the role of UBD as a metabolic regulator in tumor immune therapy." (PMID 40692714, 2025). "We found that UBD expression was significantly associated with tumor size (p = 0.037) and TNM stage (p = 0.017) but not with patient sex, age or tumor location." (PMID 34350116, 2021). "We speculate that increased UBD expression may promote an immune response in the tumor microenvironment, which suppresses tumor growth." (PMID 34458266, 2021). "Correlations of UBD expression with cell proliferation and advancing tumour stages suggests that UBD may contribute to the progression of colon carcinogenesis." (PMID 20808312, 2010). "It has been suggested that UBD expression may be related to other biomarkers used to predict tumour metastasis, such as CD44v6, nm23, MTA1 and matrix metalloproteases." (PMID 20808312, 2010). "Positive (weak and strong) UBD expression was strongly associated with an increased risk of tumour recurrence as compared with negative UBD expression (RR 3.786; 95% CI 1.912–7.497; P<0.001)." (PMID 20808312, 2010). "Additionally, developing novel drugs targeting UBD and its regulated metabolic pathways could offer a new direction for tumor immunotherapy." (PMID 40692714, 2025). "However, a marked increase in tumor size and weight could be seen in the UBD overexpression group compared with the control group." (PMID 34350116, 2021). "RT-qPCR analysis revealed a significant upregulation of UBD gene expression in ESCA tumor tissues, with expression levels positively correlating with tumor staging." (PMID 41347086, 2025). "WB analysis demonstrated upregulated UBD protein expression levels in ESCA tumor samples, with expression levels progressively increasing in correlation with advancing tumor stages." (PMID 41347086, 2025). "In the total of 84 HPV-regulated genes, only four genes (EGFR, SNF, UBD, and VCAM1) were differentially expressed when compared with HPV− tumor." (PMID 34646755, 2021). "Evidence has confirmed that UBD is overexpressed in a variety of tumors, including CRC, and is related to tumor proliferation, metastasis and prognosis." (PMID 34350116, 2021). "All the genes identified to activate the tumor microenvironment pathway were highly upregulated at day 93 PI except secreted phosphoprotein 1 (SPP1), Indoleamine 2,3-dioxygenase 1 (IDO1), UBD and CD274, which were also highly upregulated at day 45 PI." (PMID 34946170, 2021). "Moreover, our study further confirms that UBD modulates immune cell polarization via glycolytic metabolism, thereby altering the TME and providing a novel mechanistic insight into tumor immune evasion." (PMID 40692714, 2025). "The results from the TCGA/GTEX datasets and our clinicopathological specimens also confirmed that the expression level of UBD in CRC tumor tissues was significantly higher than that in nontumor tissues." (PMID 34350116, 2021). "UBD was overexpressed in CRC tumor tissues compared with nontumor tissues, and its overexpression was positively associated with the tumor size and TNM stage of CRC patients." (PMID 34350116, 2021). "In this study, we have confirmed that Vx3(A7) protein is an effective tool to enrich Ub-Ps from whole tumor cell lysate compared with other kinds of UBD proteins such as TUBEs (data not shown)." (PMID 25886865, 2015). "Patients with weak and strong UBD staining in primary tumours had higher recurrent rates than did patients with negative primary tumour staining (weak 38/68, 55% strong 26/60, 43% negative 14/67, 20% P=0.006)." (PMID 20808312, 2010).
tumor (continued). "CNV score analysis revealed that Malignant, CASC15+KLK6+EPC, and UBD+S100A11+EPC exhibited significantly higher CNV scores than other subpopulations, indicating that these cells have a higher malignant potential and may play a key role in tumor progression." (PMID 40932351, 2026). "The expression of UBD was clearly upregulated in tumor tissues compared with nontumor tissues." (PMID 34350116, 2021). "Patients with negative tumour UBD expression had a better 5-year disease-free survival (DFS) and overall survival (OS) rate than did the group with positive UBD expression (DFS: 83% negative vs 57% positive; OS: 85% vs 63% P=0.001, respectively)." (PMID 20808312, 2010).
infection (16 papers, 2006 to 2025). The state of being infected such as from the introduction of a foreign agent such as serum, vaccine, antigenic substance or organism. "However, the ubiquitin-like modifier gene, UBD, was more highly expressed in the susceptible animals prior to infection but more highly expressed in resistant animals after infection with gastrointestinal nematodes." (PMID 16515715, 2006). "Therefore, while UBD is expressed more highly in naïve susceptible animals, upon infection with nematodes the resistant animals may induce UBD expression to a higher level than the susceptible animals in a TNFα-dependent manner." (PMID 16515715, 2006). "The upregulation of ISGs (i.e. CXCL9, IRGM1, PSMB9, STAT1 and UBD) in DBA/2 compared to C57BL/6 mice was confirmed by RT-qPCR at all days post-infection." (PMID 23006927, 2012). "In the PS chimpanzee, the UBD expression level remained close to baseline levels in the first eighteen days post-infection, and then the UBD expression steadily increased during the remaining time course of HCV infection." (PMID 19149867, 2009).
inflammation (3 papers, 2020 to 2023). Aberrant reaction of the microcirculation characterized by movement of fluid and leukocytes from the blood into extravascular tissues. "UBD expression was also reportedly downregulated in the colonic mucosa of patients with UC, suggesting its role in the pathogenesis of colonic inflammation." (PMID 36699607, 2022). "This is the first depiction of the expression of UBD, UBE2L3, CUL2, and HSP5 genes in the colonic mucosa from patients with UC, suggesting that these genes could be involved in the pathogenesis of colonic inflammation in patients with UC." (PMID 32410873, 2020).
reproductive diseases (1 paper, 2024). "Cows might experience such intervals due to reproductive diseases impacting the health of the animal, the unit in which cows were housed, or their interactions, but that was not the case for both the SREBF1 and UBD SNPs." (PMID 39184351, 2024).
UBD also shares sentences with these, for which no sentence is quoted: fibrosis (4 papers); liver disease (4); Ventricular arrhythmia (4); chronic kidney disease (3); kidney diseases (3); non-small cell lung carcinoma (3); osteosarcoma (3); alcoholic fatty liver disease (2); alcoholic hepatitis (2); alcoholic liver diseases (2); atherosclerosis (2); cardiac arrhythmia (2); cardiovascular disease (2); central nervous system cancer (2); Cirrhosis (2); COVID-19 (2); fatty liver disease (2); heart failure (2); Hepatic steatosis (2); ischaemia (2); nonalcoholic fatty liver disease (2); renal fibrosis (2); Ureteral obstruction (2); acute leukemia (1); acute pancreatitis (1); Arrhythmia (1); asthma (1); bacterial infection (1); benign breast tumors (1); cardiac hypertrophy (1).
A further 45 diseases each share a sentence with UBD in 1 paper.